CRP (C-reactive protein)
Diseases named in the same sentence as CRP in open-access papers (continued):
Sharing a sentence is not in itself a finding about the gene and the disease.
breast cancer (continued). "Serum NF-κB, TNF-α, sTRAIL, IL-6, PTX-3, PCT, and serum CRP levels were measured using enzyme-linked immunosorbent assay (ELISA) in 40 patients with breast cancer, 40 patients with colon cancer and 30 healthy controls." (PMID 33776564, 2021). "A meta-analysis demonstrated that elevated plasma CRP levels were associated with an increased risk for breast cancer (OR, 1.22), with the association strongest in Asian women (OR, 1.57)." (PMID 34359821, 2021). "Physical activity reduces levels of chronic inflammation factors, e.g., C-reactive protein (CRP), which can contribute to breast cancer risk." (PMID 34462889, 2021). "Future studies seeking to identify subjects on the basis of an inflammatory mediated risk of relapsed breast cancer should therefore strongly consider checking CRP." (PMID 33483516, 2021). "Various epidemiological studies have revealed a positive connection between hs-CRP level and breast cancer risk." (PMID 34711013, 2021). "No other subgroups revealed a statistically significant association between genetically determined chronic inflammation or CRP levels and breast cancer risk." (PMID 33614510, 2020). "Mendelian randomization analysis: the effect of genetically predicted CRP phenotype on breast cancer risk by ER/PR and HER2/neu status." (PMID 33614510, 2020). "Eight of the twelve studies considered associations of CRP with breast cancer risk by different stratifying factors, including menopausal status, body size, and use of HRT." (PMID 32731638, 2020). "Our findings suggest potential interventions targeting CRP–inflammatory markers to reduce breast cancer risk." (PMID 33614510, 2020). "A 1-unit increase in the log-transformed genetically elevated CRP level was associated with 80% or more increased risk for ER/PR-positive breast cancer (IVW-HR1st-stage = 1.79, 95% CI: 1.17–2.76; WM-HR2nd-stage = 2.11, 95% CI: 1.00–4.46)." (PMID 33614510, 2020). "Studies have shown that increased levels of pro-inflammatory cytokines and CRP have been linked to increased cancer risk and reduced overall survival of breast cancer." (PMID 33108715, 2020). "Candidate predictive biomarkers to date include elevated CRP in pancreatic and breast cancers, PTPRT/D mutations in HNC, and a JAK1 S703I mutation in HCC, and assessments of biologically plausible biomarkers that predict clinical responses are needed." (PMID 33521321, 2020). "Reports indicate that elevated levels of plasma IL-6 and CRP are associated with reduced progression free and overall survival in patients with breast cancer who were treated with anti-PD-L1 immunotherapy." (PMID 33123173, 2020). "Findings were inconsistent across the five studies that examined the association of CRP with breast cancer risk stratified by menopausal status." (PMID 32731638, 2020). "CRP is an acute-phase reactant inflammatory and established independent diagnostic marker for breast cancer development, as it is synthesized in hepatocytes in response to leucocyte-released cytokines within a tumor microenvironment." (PMID 32532068, 2020). "In MR analyses, there was little evidence to suggest associations of any of the adipokines or CRP with overall breast cancer risk." (PMID 32134113, 2020). "Each meta-analysis included a common core of prospective studies, and all found a statistically significant positive association between circulating CRP levels and breast cancer risk." (PMID 32731638, 2020). "Three meta-analyses published in 2015 each found a consistent, positive association between elevated blood levels of CRP and breast cancer risk." (PMID 32731638, 2020). "Controversy regarding an association between CRP and other types of cancer, namely prostate and breast cancer, also exists." (PMID 33256656, 2020). "Given these inconsistencies across studies, further research is needed to confirm the positive relationship between blood levels of CRP and breast cancer risk." (PMID 32731638, 2020).
breast cancer (continued). "Collectively, these findings do not support an important aetiological role of various adipokines or CRP in overall or oestrogen receptor‐specific breast cancer risk." (PMID 32134113, 2020). "MR evaluates the exposure (e.g., CRP) on an outcome (e.g., breast cancer risk) using genetic variants as an instrumental variable." (PMID 33614510, 2020). "Only one marker, C-reactive protein, was studied extensively (measured in 13 of the 16 publications), and had some evidence of a positive association with breast cancer risk." (PMID 32731638, 2020). "A meta-analysis similarly indicated that for each doubling of CRP concentration, risk of any breast cancer and postmenopausal breast cancer was elevated 7% (95% CI 2–12%) and 6% (95% CI 1–11%), respectively." (PMID 33004039, 2020). "Circulating adipokines and C‐reactive protein (CRP) have been linked to breast cancer risk in observational epidemiological studies." (PMID 32134113, 2020). "Estrogen-only users for ≥5 years had more profound CRP-decreased breast cancer risk in dose–response fashion, whereas past OC users for ≥5 years had CRP-increased cancer risk." (PMID 33614510, 2020). "In lifestyle-stratification analyses, genetically elevated CRP decreased risk for breast cancer in exogenous estrogen-only, estrogen + progestin, and past oral contraceptive (OC) users, but only among relatively short-term users (<5 years)." (PMID 33614510, 2020). "In patients with elevated CRP, ruxolitinib combined with capecitabine was associated with improved health-related quality of life in breast cancer." (PMID 33521321, 2020). "Genetically elevated CRP levels were strongly associated with increased breast cancer risk in past OC users for ≥5 year (IVW-HR2nd-stage = 2.14, 95% CI: 1.11–4.10, after exclusion of pleiotropic SNPs)." (PMID 33614510, 2020). "We detected a substantially reduced risk of breast cancer in relation to CRP in E-only, E + P, and past OC users, but only among relatively short-term users (<5 years)." (PMID 33614510, 2020). "Our MR analyses in up to 122,977 breast cancer cases and 105,974 controls do not support an important aetiological role of six adipokines or CRP in breast cancer risk." (PMID 32134113, 2020). "This study aimed to explore the effect of dietary magnesium intake on breast cancer risk both directly and indirectly via its effect on inflammatory markers C-reactive protein (CRP) and interleukin-6 (IL-6)." (PMID 30962499, 2019). "The objective of this study was to conduct a cross-sectional analysis to determine the associations between dietary acid load and CRP and HbA1c, using data from a large cohort study of breast cancer survivors, the Women’s Health Eating and Living (WHEL) study." (PMID 31443226, 2019). "This study showed that dietary magnesium intake was inversely associated with breast cancer risk and that higher CRP level was a risk factor for breast cancer development." (PMID 30962499, 2019). "Compared with participants with CRP values ≤3000 ng/mL (the lower group), those with CRP values >3000 ng/mL (the higher group) had a 1.43 times higher breast cancer risk (95% CI = 1.04–1.97)." (PMID 30962499, 2019). "The positive associations between dietary acid load and CRP and HbA1c have important implications for breast cancer survivors." (PMID 31443226, 2019). "To date, four meta-analyses have summarised previous studies, three of which consistently supported a positive association between the CRP level and breast cancer risk as observed in our study." (PMID 30962499, 2019). "Our current data provides evidence that CRP is associated with RT-related pain in breast cancer patients." (PMID 31138314, 2019). "The results also provided evidence of a positive association between the CRP level and breast cancer risk among Chinese women." (PMID 30962499, 2019). "Path analysis revealed that dietary magnesium affected breast cancer risk both directly and indirectly by influencing the CRP level." (PMID 30962499, 2019).
breast cancer (continued). "Several studies have attempted to investigate the association between the circulating CRP level and breast cancer risk, most of which have reported consistent results; however, few such studies have been conducted on Chinese populations." (PMID 30962499, 2019). "The results indicate that a direct negative association and an indirect association through influencing the CRP level were observed between dietary magnesium intake and breast cancer risk." (PMID 30962499, 2019). "A positive association was found between the CRP level and breast cancer risk (adjusted OR = 1.43, 95% CI = 1.02–2.01)." (PMID 30962499, 2019). "Direct and indirect effects of dietary magnesium were statistically significant for breast cancer risk with estimates of −0.21 and −0.01, and the CRP level played a mediating role in the association between dietary magnesium intake and breast cancer risk." (PMID 30962499, 2019). "Our study is the first to demonstrate positive associations between dietary acid load and CRP and HbA1c in breast cancer survivors." (PMID 31443226, 2019). "In summary, our current data show a significant association between elevated pre-RT CRP and RT-related pain in breast cancer patients." (PMID 31138314, 2019). "There is growing evidence that an increased CRP level is associated with the risk of colorectal and lung cancers, but evidence about the association of CRP level with breast cancer risk is inconsistent." (PMID 30962499, 2019). "The results showed that dietary magnesium intake affected breast cancer risk both directly and indirectly by modifying the CRP level." (PMID 30962499, 2019). "In conclusion, this study indicated that a higher dietary magnesium intake was associated with a lower breast cancer risk both directly and, in part, indirectly via reduction in the CRP level." (PMID 30962499, 2019). "A study on 59 samples found that CRP in NAF was positively related to the Gail model for breast cancer risk." (PMID 29344009, 2018). "For example, rs1333048 has been shown to be associated with the level of highly sensitive C-reactive protein (hsCRP), which is a biomarker for systemic inflammation and breast cancer susceptibility." (PMID 29802154, 2018). "A vast majority of the studies looking at the association between inflammation and BC risk used the CRP and a recent meta-analysis concludes a modest statistically significant positive association between CRP concentration and breast cancer risk." (PMID 30018397, 2018). "Elevated CRP levels at the time of diagnosis of breast cancer are associated with reduced overall and disease-free survival and an increased risk of death from breast cancer." (PMID 28851415, 2017). "Among postmenopausal women, high CRP was associated with increased breast cancer risk, and high adiponectin was associated with decreased risk." (PMID 28983080, 2017). "One study identified an interaction between eating frequency and an inflammatory biomarker, C-reactive protein (CRP), as a putative factor associated with breast cancer." (PMID 29215604, 2017). "Elevated serum levels of C-reactive protein (CRP) at the time of diagnosis were observed and associated with shorter disease-free survival and overall survival of breast cancer patients." (PMID 29061183, 2017). "Our finding of a direct association between plasma CRP and risk of postmenopausal breast cancer is in line with the findings of two recently published meta-analyses." (PMID 28983080, 2017). "Elevated levels of serum amyloid A (SAA) and C-reactive protein (CRP) are associated with significantly increased risk of death among breast cancer patients (HR = 3.15, 95 % CI 1.73–5.65 and HR = 2.27, 95 % CI 1.27–4.08, respectively)." (PMID 26970739, 2016). "The meta-analysis was based on twelve studies and reported a 7% increase in breast cancer risk when the concentration of circulating C-reactive protein (CRP) was doubled." (PMID 27391324, 2016).
breast cancer (continued). "But women with body mass index above 25 Kg/m2 and history of past smoking were found to have a significant association between CRP and risk of breast cancer." (PMID 26693355, 2015). "An alternative way to eliminate reverse causality and to minimize residual confounding would be to investigate the associations of breast cancer with genetic variants known to be associated with circulating CRP." (PMID 26001129, 2015). "During the last decade, several epidemiologic studies have appraised the associations between CRP and breast cancer risk." (PMID 26001129, 2015). "Overall, the result supported a significant positive association between the elevated levels of CRP and an increased risk of breast cancer." (PMID 26001129, 2015). "Numerous prospective epidemiological studies have observed the association of CRP at the time of diagnosis of breast cancer with the prognosis of the disease." (PMID 26693355, 2015). "Findings of WHEL study reported increased 2-fold risk of all-cause and breast cancer-specific mortality and 67% risk of additional breast cancer-related events in subjects with raised CRP levels during postdiagnosis period." (PMID 26693355, 2015). "So Guo and associates conducted a meta-analysis of 8 cohort and 7 case-control studies to assess the role of CRP in predicting breast cancer risk." (PMID 26693355, 2015). "The present review is aimed at elucidating the role of C-reactive protein, as an inflammatory risk marker and prognostic predictor of breast cancer." (PMID 26693355, 2015). "The present review is aimed at elucidating the role of C-reactive protein, an inflammatory risk marker and prognostic predictor of breast cancer as well." (PMID 26693355, 2015). "The potential utility of CRP as a risk predictor for breast cancer is questionable in clinical practice." (PMID 26693355, 2015). "In conclusion, the findings of this meta-analysis indicated that elevated CRP levels was associated with increased risk of breast cancer, especially among the Asian population." (PMID 26001129, 2015). "In a prospective cohort study in breast cancer patients, elevated CRP and serum amyloid A were associated with reduced overall survival." (PMID 26345187, 2015). "The overall estimate indicated an 16% increase in risk of breast cancer for a natural log unit increase in CRP levels." (PMID 26001129, 2015). "The meta-analysis indicated that elevated CRP levels was associated with increased risk of breast cancer." (PMID 26001129, 2015). "Out of 15 studies, two studies had shown negative, statistically insignificant association between one unit change in ln CRP and breast cancer." (PMID 26693355, 2015). "Prediagnostic high-sensitivity CRP concentrations (OR = 1.22, 95% CI: 1.10-1.35) was superior to common CRP (OR = 1.08, 95% CI: 1.01-1.15) in predicting breast cancer risk." (PMID 26001129, 2015). "In the present review, we intended to evaluate the role of CRP in every aspect of breast cancer, from its usefulness in risk prediction, diagnosis, prognosis, and therapeutics." (PMID 26693355, 2015). "Estimation of CRP can be looked at as a simple, cost-effective, easily available screening test to assess future risk of breast cancer." (PMID 26693355, 2015). "The association between CRP level and breast cancer survival has until now been examined mainly in patients with adjuvant systemic treatment." (PMID 25340395, 2014). "CRP is an inflammatory effector that has been linked to breast cancer risk and poorer prognosis, with higher circulating levels observed in AA women compared to EAs." (PMID 23991131, 2013). "Independent effect of CRP and alterations in the levels of both leptin and adiponectin were altogether accompanied by an increase in breast cancer risk incidence." (PMID 23374911, 2013). "In this cohort of breast cancer survivors, we found a significant association between acute phase proteins (CRP or SAA) and adiposity as measured by DEXA." (PMID 22873489, 2012).
breast cancer (continued). "Elevated CRP levels at the time of diagnosis of breast cancer are associated with reduced overall and disease-free survival and with increased risk of death from breast cancer." (PMID 21639875, 2011). "CRP serum levels have been associated with breast cancer and increased circulating levels of CRP have also been detected in more advanced stages of breast malignancy, suggesting the potential use of CRP as a biomarker of disease prognosis." (PMID 22276018, 2009). "IL-6 controls the hepatic production of CRP, which is a risk factor for insulin resistance, breast cancer and cardiovascular diseases." (PMID 19545451, 2009). "This is of special interest because altered levels of leptin and adiponectin are consistent with the elevated breast cancer risk in addition to the independent effect of CRP in enhancing the breast cancer risk." (PMID 19545451, 2009). "In breast cancer survivors, a high-quality diet that is typically rich in fruits, vegetables, whole grains, and polyunsaturated fatty acids has been reported to be associated with lower levels of pro-inflammatory biomarkers (e.g., CRP and TNF-α)." (PMID 40289959, 2025). "In our NWO-biomarkers analyses, NWO was linked to 34 identified biomarkers, of which three inflammation markers (monocyte count, neutrophil count, and C-reactive protein), and one ketone body metabolite (β-Hydroxybutyrate) also indicated a positive association with postmenopausal breast cancer." (PMID 39609539, 2025). "Elevated CRP levels have been shown to be associated with poor survival rates in various cancers, including renal carcinoma, lung cancer, pancreatic cancer, and breast cancer." (PMID 40716028, 2025). "Some scholars have also suggested that excessive sleep may lead to elevated levels of systemic inflammation and an increase in some inflammatory biomarkers, such as CRP and IL-6, which may predispose individuals to breast cancer." (PMID 40735026, 2025). "The inverse association between CRP and breast cancer in the extremely high group could possibly be explained by the inverse association between breast cancer and autoimmune disease, as these patients were characterized by high levels of CRP." (PMID 38360584, 2024). "Integrating measurements of testosterone, SHBG, and CRP into diagnostic models could enhance breast cancer detection, particularly among individuals of normal weight." (PMID 39791640, 2024). "The results of the present work support the hypothesis that greater adherence to Mediterranean-type dietary pattern may lead to a reduction in breast cancer risk through modulation of the CRP concentration." (PMID 38674877, 2024). "Furthermore, regarding breast cancer, increased CRP values are associated with reduced overall disease-free survival and higher mortality, yet hsCRP seems not to be predictive of post-menopausal breast cancer occurrence in apparently healthy women." (PMID 37873776, 2023). "Further, in another study analyzing the relationship between fat distribution and level of biomarkers in breast cancer showed that changes in abdominal fat were associated with changes in CRP levels, while the final reviewed study showed a positive relation between BMI and CRP." (PMID 37181043, 2023). "In addition to the known association between CRP and breast cancer risk, we observed that higher baseline serum CRP levels were associated with a higher risk of breast cancer mortality." (PMID 38000092, 2023). "Studies have shown that higher CRP-to-albumin ratios are associated with relatively worse prognosis from early-stage to metastatic cancers, and across all types, including genitourinary, gastrointestinal, lung, and breast cancers 18-23." (PMID 37476185, 2023).